ARG1 (arginase 1)
Diseases named in the same sentence as ARG1 in open-access papers (continued):
Sharing a sentence is not in itself a finding about the gene and the disease.
glioblastoma (continued). "Hereby, we identify arginase-1+ TAMs as a potential therapeutic target in glioblastoma." (PMID 32498400, 2020). "To determine whether the increase of arginase-1 expression in TAM-derived exosomes is responsible for the promotion of glioblastoma cell proliferation, we incubated tumor cells in the presence of arginine or the arginase inhibitor (nor-NOHA) for 24 h and measured cell viability." (PMID 32498400, 2020). "Therefore, in human glioblastoma, neutorphils may play a more active role in Arg1-mediated local immunosuppression." (PMID 27936099, 2016). "A prognostic model for glioblastoma patients stemmed out from a Cox multiple analysis, highlighting the role of MDSC, p-STAT3, and ARG1 activity together with clinical parameters in predicting patient’s outcome." (PMID 35069595, 2021).
colorectal cancer (20 papers, 2020 to 2025). A primary or metastatic malignant neoplasm that affects the colon or rectum. "Our study aimed to investigate the balance between nitric oxide synthase-2 (NOS2) and arginase-1 (ARG1) expression and its association with immune contexture and clinical outcome in cetuximab-treated colorectal cancer patients." (PMID 41573553, 2025). "Higher ARG1 expression was associated with lower survival probability, suggesting a link to poor prognosis in colorectal cancer." (PMID 38012650, 2023). "Together, these data indicated that ARG1, primarily derived from TAMs, was associated with immune checkpoints and T cell exhaustion in colorectal cancer." (PMID 38012650, 2023). "In contrast, tumor Arg-1 expression in colorectal cancer was associated with high-stage tumors, lymph node metastases and reduced survival." (PMID 38001706, 2023). "We also used the GSE4107 dataset to analyze the expression level of ARG1 in colorectal cancer, which was consistent with the current results, and ARG1 was highly expressed in colorectal cancer." (PMID 38012650, 2023). "Firstly, through bioinformatics, the data suggested that ARG1 expression was positively correlated with immune checkpoints in colorectal cancer and other tumors." (PMID 38012650, 2023). "Macrophages cocultured with MTA1-overexpressing colorectal cancer cells significantly upregulated the M2-like macrophage markers Arg-1, CD206 and Ym1 but significantly downregulated the expression of the immunostimulator IL-6." (PMID 35350571, 2022). "A recent study demonstrated that activation of NOD1 facilitated oncogenesis by promoting autophagy-dependent macrophage reprogramming and triggering myeloid-derived suppressor cell (MDSC) expansion and immunosuppressive ability through arginase-1 activity in colorectal cancer." (PMID 36920176, 2023). "The overexpression of ARG1 is related to poor prognosis in patients with colorectal cancer." (PMID 33915902, 2021). "Similar results were observed in patients with colorectal cancer, where a higher ARG1 mRNA level was associated with worse OS and disease-free survival (DFS), or classic Hodgkin lymphoma, where an elevated level of ARG1 negatively influenced PFS." (PMID 33807310, 2021). "Notably however, a recent study indicated that high intratumoral neutrophil numbers expressing ARG1 correlate with better survival of patients with colorectal cancer." (PMID 32499785, 2020). "The correlation between arginase-1 (ARG1) and T cells was computed based on the colorectal cancer patients in TCGA database." (PMID 38012650, 2023). "Histopathology and immunohistochemistry (CK7, CK20, CDX2, SATB2, Arginase-1) confirmed that the intestinal lesions were metastases from gastric cancer rather than synchronous primary colorectal cancers." (PMID 41159019, 2025). "SMAD4 deletion promotes colorectal cancer (CRC) expression of C-C Motif Chemokine Ligand 15 (CCL15) and recruits the CCR1 TAN (CCL15-CCR1 axis) with arginase-1 (ARG-1) and matrix metalloproteinase 9 (MMP-9) activities, thereby forming a pre-metastatic niche for disseminated tumor cells (e." (PMID 40160822, 2025). "In summary, ARG1 was positively correlated with TIM3, TIGIT and ICOS in colorectal cancer." (PMID 38012650, 2023). "Besides the ability to inhibit cytotoxic T cell responses, PGE2 suppressed RIPK3 expression in MDSC and colorectal cancer cells and induced NF-κB/COX-2 and expression of arginase 1 (ARG-1)." (PMID 32931721, 2020). "When we treated BMDMs with supernatants of murine colorectal carcinoma CT26 cells, again we noted enhanced induction of Arg1 in the absence of FIH (FIH+/+ vs. FIHΔ1-2/Δ1-2 0.128 vs. 0.293, P = 0.047, t test)." (PMID 38422022, 2024). "The effect of inhibiting arginase 1 (ARG1) and nitric oxide synthase 2 was assessed using the small molecule inhibitors NOHA and L-NMMA, respectively, and was found not to rescue T cell proliferation inhibited by colorectal cancer patient’s CD14 + cells." (PMID 34727230, 2022).
viral infection (20 papers, 2012 to 2025). "The effect of basal IL-4 on Arg1 expression and pathology suggests that additional signals derived from the virus infection, or the immune response to it, are likely required to combine with IL-4 for the effects seen." (PMID 40854598, 2025). "For instance, the ARG1 gene, which modulates L-arginine metabolism, balances inflammation and tissue repair during viral infections possibly mitigating hyperinflammation or facilitating viral persistence." (PMID 40124360, 2025). "Post PCV2 infection, we identified 199 differentially expressed lncRNAs, which appear to modify genes associated with viral infection, such as SOD2, TNFAIP3, ARG1, SERPINB2, VLDLR, HSPA5, and LCN2." (PMID 30863688, 2019). "In contrast, H1N1/WSN and H5N2 virus infection induced a M2 like phenotype, which is characterized by increased expression of arginase 1 (ARG1) at 2hpi and had a similar metabolic profile as unpolarized (inactivated) macrophages (mock infected)." (PMID 28558796, 2017). "This phenomenon of Arg1-mediated T cell suppression has also been recognized in human viral infections." (PMID 25250029, 2014). "Arg1 activity not only has important wound healing functions but can also inhibit the antiviral immune response during some viral infections." (PMID 25250029, 2014). "In addition to wound healing properties, ARG1 activity can also suppress the antiviral immune response during some viral infections." (PMID 35284643, 2022). "Markers of polymorphonuclear myeloid-derived suppressor cells (PMN-MDSCs), CEACAM8 (CD66B) and OLR1 (LOX-1), and markers of monocytic MDSCs (M-MDSCs), IL-4R, ITGAM (CD11B), including a functional marker of MDSCs, ARG1, were positively correlated with the severity of viral infection." (PMID 33765435, 2021). "For example, TNFAIP3 is involved in influenza A virus infection, whereas ARG1 suppresses arthritogenic alphavirus infection Therefore, PCV2 infection-associated lncRNAs may modulate viral infection through regulating these targeted genes." (PMID 30863688, 2019). "While the role of Arg-1 in viral infections is not well understood, it has been shown that Arg-1 overexpression blocks Chikungunya virus (CHIKV) clearance and tissue pathology, suggesting a pathogenic role for Arg-1 after infection." (PMID 29077752, 2017). "In this review, we highlight recent studies of viral infections where myeloid cell polarization – resulting in expression of iNOS or Arg1 – contribute to viral control or the development of chronic virus infection and mediate the resolution of tissue damage or cause immunopathology." (PMID 25250029, 2014). "Clearly, iNOS- and/or Arg1-mediated responses are important in many viral infections." (PMID 25250029, 2014). "However iNOS and Arg1 activity can be both beneficial and detrimental during certain viral infections." (PMID 25250029, 2014). "However, NO production can also result in immunopathology in some virus infections, and the suppressive functions of Arg1-expressing macrophages can promote immunopathology." (PMID 25250029, 2014). "Increasing evidence suggests that myeloid cell programing, iNOS, and Arg1 contribute to the pathogenesis of numerous virus infections, suggesting that therapies that target these cells and pathways may be beneficial for the treatment of some virus diseases." (PMID 25250029, 2014). "In summary, we have demonstrated that T-bet activity during a chronic viral infection can impede antiviral immune control by driving the development of highly differentiated TH1-like cells that express genes encoding inhibitory molecules, including IL-10 and Arg1." (PMID 37440306, 2023). "These situations can include viral infection, exposure to high levels of fatty acids during pathogenesis, oxidative stress during inflammation or amino acids starvation, mediated by amino acid–degrading enzymes, such as arginase 1 or IDO, which are induced during infection or cancer development." (PMID 33443099, 2021).
viral infection (continued). "Furthermore, as previously demonstrated, Fcgr1 makes a contribution to arthritis pathology; Clec4a2 and Clec4d play essential roles in maintaining the homeostasis of immune system; Arg1 activity is important for wound healing functions and immune response to viral infections." (PMID 29197380, 2017). "Due to the overlap in immunosuppressive mechanisms of iNOS- and/or Arg1-expressing suppressor cells, therapeutic strategies under development to limit the immunosuppressive effects of myeloid cells in cancer may be beneficial in treating persistent/chronic virus infections." (PMID 25250029, 2014). "Markers of AAM, Arginase-1, FIZZ1, and MR were constitutively elevated and increased later during viral infection, suggesting adult AM are responsible for both viral clearance and containment of a robust inflammatory response." (PMID 22792355, 2012). "During viral encephalitis, the major group of MHC class II proteins, as well as the costimulatory molecules CD40, CD16, CD32, and CD86, are expressed on the surface of activated M1 microglia following viral infection, while M2 microglia typically express CD206 and ARG-1." (PMID 36918933, 2023). "In addition to the actions of iNOS and Arg1, MDSC-like cells can employ other mechanisms to promote chronic viral infections, which were recently reviewed by Goh and colleagues." (PMID 25250029, 2014). "In this review, we will discuss a variety of viral infections, including HIV, SARS-CoV, LCMV, HCV, RSV, and others, where myeloid cells influence the control and clearance of the virus from the host, as well as the severity and resolution of tissue damage, via the activities of iNOS and/or Arg1." (PMID 25250029, 2014). "Arg1 expression was not notably changed after virus infection." (PMID 25105760, 2014).
gastric cancer (19 papers, 2014 to 2026). A primary or metastatic malignant neoplasm involving the stomach. "It has been reported that high arginase 1 (ARG1) expression can be correlated with the increase in MDSCs in gastric cancer patients." (PMID 38791327, 2024). "Other pathways involved in MDSC Arg1 expression include the microRNA-107 (miR-107) pathway which induces expansion and Arg1 levels of MDSCs in gastric cancer." (PMID 38464388, 2024). "The results indicated that the conditioned medium with GRP78-overexpressing gastric cancer cells promoted the expression of the TAM/M2 marker Arg1 and suppressed the expression of the M1 marker iNOS in macrophages." (PMID 36838713, 2023). "In this coculture system, the downregulation of MIF in MAPK4-depleted BGC-823 cells not only robustly inhibited MIF secretion but also significantly suppressed Arg1 expression in BMDMs and gastric cancer cell invasion." (PMID 36797541, 2023). "In gastric cancer, serum-derived IL-6 activates and induces MDSCs, which express arginase 1, via the PI3K-Akt signaling pathway, thereby suppressing cytotoxic T cell functionality." (PMID 33981768, 2021). "Data confirmed that there was a sufficiently high amount of ARG1 and NOS2 to cause T cell function inhibition in HLA-DR-/low mononuclear cells under gastric cancer conditions." (PMID 32415175, 2020). "On the whole, ARG1-expressing MDSCs were mainly naïve MDSCs, early-stage MDSCs and monocytic MDSCs in gastric cancer tissue." (PMID 32415175, 2020). "While we know that there are a large number of circulating and tumor-infiltrating MDSCs existing in gastric cancer (GC) patients, the phenotypic characteristics and arginase 1 (ARG1) expression levels of these MDSCs remain very unclear." (PMID 32415175, 2020). "Meanwhile, the mRNA expression levels of Arg1 and iNOS which reflected the level of MDSCs or M2 macrophages were significantly increased in patients with gastric cancer." (PMID 24741632, 2014). "In addition to M2 TAMs, ARG1 is an accepted marker for MDSCs in gastric carcinoma, non-small cell lung carcinoma, and pancreatic adenocarcinoma or a marker of neutrophils." (PMID 33807310, 2021). "In gastric cancer tissues, high expression levels of Ym-1, Fizz-1, arginase-1, and CCR-2, as well as a low expression level of iNOS, were verified, and co-localization of GC-MSCs and tumor-associated macrophages (TAMs) was observed by dual immunofluorescence histochemistry." (PMID 31801938, 2019). "In this system, the depletion of MAPK4 in BGC-823 cells and MKN45 cells not only significantly enhanced the expression of arginase 1 (Arg1, a marker for activated TAM) and CD206 in BMDMs but also robustly promoted gastric cancer cell invasion." (PMID 36797541, 2023). "In patients with gastric cancer (GC), IL-6 and IL-8 activate CD45+CD33lowCD11bdim MDSCs, thereby inducing Arg1 release accompanied by activation of the PI3K-AKT signaling pathway." (PMID 32488850, 2020). "Compared with the adjacent non-cancerous tissues, significantly higher levels of Ym-1, Fizz-1, arginase-1 and CCR-2, the M2 macrophages’ markers, were observed in gastric cancer tissues with GC-MSCs infiltration." (PMID 31801938, 2019). "We observed that 5-FU-resistant gastric cancer cells were more effective than 5-FU-sensitive gastric cancer cells in skewing macrophages to M2 polarization, characterized by up-regulated expression of CD163, CD206, IL-10, Arg-1 and VEGF-A and down-regulated expression of CD86, TNF-α and IL-12." (PMID 36151545, 2022).
Hyperammonemia (19 papers, 2013 to 2026). An increased concentration of ammonia in the blood. "Some reports have described cases of ARG1 deficiency presenting with hyperammonemia in the neonatal period or early infancy." (PMID 34646736, 2021). "Clinical features of UCDs other than ARG1 deficiency are generally related to recurrent episodes of hyperammonemia." (PMID 34646736, 2021). "The major cause of death in Arg1 KO mice is hyperammonemia resulting from the defect of the liver urea cycle." (PMID 32499785, 2020). "A mouse model of arginase-1 deficiency was developed in 2002, but the mice died approximately two weeks after birth from apparent hyperammonemia." (PMID 25938595, 2015). "Unlike the preponderance of UCD cases that present in the neonatal period with bouts of hyperammonemia and severe metabolic crisis, arginase-1 deficiency typically is discovered from late infancy to 2–4 years of age with signs that can resemble cerebral palsy." (PMID 25938595, 2015). "As ARG1-deficient patients rarely develop hyperammonemia crises, they have a prolonged life span compared to those with other urea cycle disorders." (PMID 24224027, 2013). "ARG1 deficiency leads to hyperargininemia, characterized by progressive neurological impairment, persistent growth retardation and infrequent episodes of hyperammonemia." (PMID 24224027, 2013). "Factors that can precipitate hyperammonemia in patients with arginase-1 deficiency include infections, fever, insufficient calorie intake, insufficient protein intake, general anesthesia, and high-stress conditions; all these conditions increase protein breakdown in the body." (PMID 32025996, 2019). "Arginase-1 deficiency causes hyperargininemia and hyperammonemia." (PMID 32025996, 2019). "Taken together, the deficit in coordinated neuromotor abilities observed in inducible Arg-1 deficient mice is likely resulting from a combinatorial effect of hyperammonemia, accumulation of arginine and its metabolites, such as guanidino compounds, as well as alterations of other amino acids." (PMID 24224027, 2013). "We also know that knocking out Arg1 was lethal in mice due to hyperammonemia caused by arginase deficiency, whereas the Arg2 knockout mice had intact phenotypes and Arg1/Arg2 double knockout mice exhibited the same arginase deficiency phenotype as the Arg1 single knockout mice." (PMID 33519806, 2020). "Mouse models of inducible or liver-specific Arg1 knock outs (KOs) show also hyperarginemia, while the constitutive whole body Arg1 KO mice die 2 weeks after birth due to hyperammonemia and hyperarginemia, as recently reviewed." (PMID 40729962, 2025). "These treated mice were nearly devoid of Arg1 mRNA, protein and liver arginase activity, and exhibited symptoms of hyperammonemia." (PMID 24224027, 2013). "Arginase 1 deficiency (ARG1-D) is an ultra-rare urea cycle disorder characterized by progressive spastic paraplegia, developmental delay, epilepsy, and episodic hyperammonemia." (PMID 42252709, 2026). "For patients with ARG1 deficiency, hyperammonemia is not the sole factor contributing to neurological damage." (PMID 34646736, 2021). "Low ornithine levels within liver hepatocytes, however, could be present as a result of diminished arginase activity and contribute to hyperammonemia and potentially to the lethality in the inducible Arg1 knockout mouse model." (PMID 25938595, 2015). "Deletion of both copies of arginase 1 is lethal by P10 due to hyperammonemia." (PMID 25375125, 2014). "However, Arg1 knockout animals die at the age of two weeks due to hyperammonemia resulting from an impaired urea cycle." (PMID 23840524, 2013). "All the mice were ARG1-knockout mice and survived more than 11 weeks without hyperammonemia or body weight loss after continuous treatment of human codon-optimized ARG1 mRNA LNP, which indicates a potential therapeutic strategy for the treatment of arginase deficiency." (PMID 35335310, 2022).
Hyperammonemia (continued). "Indeed, this severe phenotype can be specifically assigned to hyperammonemia, as mice lacking Arg1 develop hyperammonemia and hyperargininemia and also show a similar loss of body weight and low survival." (PMID 31653080, 2019). "Reduced expression of ASS and arginase-1 in the T1DM group indicate insufficient ammonia metabolism, which can elevate ammonia concentrations in the blood and reach toxic levels (hyperammonemia), which in turn disrupts normal central nervous system function." (PMID 28738076, 2017). "Late-onset global Arg1−/− mice and hepatocyte-specific Arg1−/− mice showed a similar phenotype characterized by hyperarginemia, hyperammonemia, and dysregulation of amino acid metabolism, but without any increase in l-ornithine." (PMID 39952693, 2025). "Hyperammonemia tended to reduce the M2 markers Arginase 1 (Arg-1) and Ym-1, but the effects were not statistically significant." (PMID 26883214, 2016).